CGA (glycoprotein hormones, alpha polypeptide)
Diseases named in the same sentence as CGA in open-access papers (continued):
Sharing a sentence is not in itself a finding about the gene and the disease.
metastatic disease (24 papers, 2008 to 2025). "Analyzing parameters correlating with CgA is crucial to support the diagnostic value of this marker and to contribute to the rapid and effective identification of patients at high risk of metastatic disease at the time of initial diagnosis." (PMID 39451760, 2024). "In the second stage, the same single-nucleotide polymorphisms (SNPs) were assessed in 127 patients with NET and analyzed in terms of clinical data (primary site, serum CgA concentration, and metastatic disease)." (PMID 36233401, 2022). "It seems to be especially useful in metastatic disease and recent data suggests that it compares better to CgA in detecting the progression of midgut NETs." (PMID 36233409, 2022). "All patients with metastatic disease had elevated CgA concentrations whereas half of patients with localized disease had elevated CgA, strengthening the idea that CgA is more sensitive in disseminated disease compared to localized disease." (PMID 33138020, 2020). "The Kaplan-Meier survival analysis included sex, CgA variation, Syn variation, Ki-67 index variation, primary tumor site and metastatic tumor site and treatment methods." (PMID 32917216, 2020). "In this study, 37.1% of cases showed the variation in CgA and 11.4% showed the variation in Syn between the primary and metastatic tumor sites." (PMID 32917216, 2020). "In Group 2, patient #2 had more than fivefold increase of CgA in the post-surgery stage, but patients #3 and #4 had normal CgA levels in the post-surgery stage, despite the presence of metastatic disease." (PMID 32291735, 2020). "In contrast, CgA levels were elevated in only 6 out of 9 patients despite the presence of metastatic disease in all patients." (PMID 30854332, 2019). "When compared to each other, cases with focal cgA positivity showed a statistically significantly higher proportion of metastatic disease (odds ratio = 6,2500, 95% CI, Chi-square = 14,510, P < 0,005) than the cases without cgA expression." (PMID 20535283, 2010). "As some studies on sporadic panNETs have demonstrated that CgA and PP can predict metastatic disease, it is possible that repeat biomarker measurement could be useful for the early detection of metastatic disease in MEN1 as well." (PMID 40455177, 2025). "Interestingly, CgA was also substantially elevated in all patients, especially with metastatic disease." (PMID 39351526, 2024). "CgA is a moderately sensitive marker, whereas specificity largely relies upon the type and tumor burden (for instance, specificity of approximately 100% has been reported in metastatic tumors)." (PMID 36950054, 2023). "Interestingly, we also found that CgA and Ki-67 variability were more common in metachronous metastatic tumors than in synchronous metastatic tumors." (PMID 32917216, 2020). "Thus, CgA positive immunostaining in Pan-NETs correlates with the elevated serum levels of CgA for diagnosing CgA-positive non-β-cell Pan-NETs and the increasing serum CgA levels indicate increasing metastatic tumor mass." (PMID 32020844, 2020). "CgA was also higher in patients with metastatic disease in multiple organs (H = 17.3; p = 0.004)." (PMID 30564197, 2018). "The Gleason score and focal cgA expression further increased the accuracy of the prediction of the outcome, as all the cases with focal NED associated with high Gleason score had metastatic disease in contrast to cases without cgA-expression and low Gleason score, all of which were non-metastatic." (PMID 20535283, 2010). "The distribution of variables such as sex, performance status, CgA immunohistochemical expression, LDH levels, metastatic disease and treatment response was similar in all three groups." (PMID 29511910, 2018). "A higher tumor load in patients with small bowel NEN as a reason for significantly higher plasma CgA levels can by excluded, because most patients with colorectal NEN showed an advanced, metastatic tumor stage." (PMID 29232390, 2017).
metastatic disease (continued). "Overall, it is recommended to perform annual biochemical testing (including plasma or urinary metanephrines and 3-methoxytyramine [3-MT], and CgA in metanephrine/3-MT-negative PGL) combined with imaging studies every 1-2 years, for early detection of tumor recurrence or metastatic disease." (PMID 39507200, 2024). "Significantly higher levels of CgA were noted in patients with metastatic disease (3444±16256 ng/ml) than those without (174±233 ng/ml, P<0.001)." (PMID 34868938, 2021). "Although CgA works well for the diagnosis of NETs, it is not a relevant biomarker at the stage of metastatic disease, a stage for which we miss curative therapies." (PMID 24282616, 2013). "All the 11 cases with high Gleason score and focal cgA expression manifested metastatic disease in contrast to the 13 cases with low Gleason score and absence of cgA expression, which all were non-metastatic." (PMID 20535283, 2010). "While focal cgA positivity appeared in 78% of metastatic tumors, all the nonmetastatic prostate cancer cases showed complete absence of cgA expression." (PMID 20535283, 2010). "It is note worthy that tumors with negative CgA staining were picked up in the early stage with minimal or organ confined disease; the positive results were obtained for locally advanced and metastatic disease (p 0.059)." (PMID 19115997, 2008).
renal failure (21 papers, 1998 to 2025). "False positive CgA test results are often caused by renal failure and hypergastrinemia." (PMID 37568540, 2023). "When we excluded patients treated with PPI or with renal failure (RF), two conditions known to be associated with increased CgA levels, we still observed a significant increase of CgA, suggesting that CLL is a condition per se sufficient to enhance the CgA levels." (PMID 27203389, 2016). "CgA can also be false-positively elevated in several clinical conditions including inflammatory bowel disease, renal failure, liver failure, or pancreatitis." (PMID 37623030, 2023). "Although it is more convenient to assess the serum level of CgA, the circulating CgA level can be affected by many factors, such as renal failure, cardiovascular diseases and the use of proton pump inhibitors." (PMID 37240468, 2023). "In patients with renal failure, serum CgA increases much more than creatinine and the other studied low-MW proteins." (PMID 35062888, 2022). "CgA shows a sensitivity of 83–89% for identifying PGLs, but it often shows false positive results because of liver or kidney failure or proton pump inhibitor therapy." (PMID 22851969, 2012). "Patient 18 with liver metastases suffered also from renal failure (glomerular filtration rate=36 ml per minute per 1.73 m2), but even then the CgA level decreased with 35%." (PMID 21989216, 2011). "Moreover, CgA levels can be affected by confounders such as renal insufficiency, atrophic gastritis, and during therapy with proton pump inhibitors." (PMID 37318593, 2023). "However, serum CgA increases in renal failure more than creatinine and the other studied low-MW proteins, β2-MG (β2 microglobulin) and TATI (tumor-associated trypsin inhibitor)." (PMID 35062888, 2022). "Increased circulating CgA levels are found in approximately 70% of NETs, both functional and non-functional—even in non-neoplastic cases, such as hepatic impairment, atrophic gastritis, and renal insufficiency." (PMID 32563832, 2020). "However, CgA measurement may result in false-positive results in patients with hepatic and renal failure, atrophic gastritis, or chronic proton pump inhibitor use." (PMID 28683830, 2017). "Increased CgA levels were likely the consequence of various factors, including CLL, renal failure, and treatment with proton pump inhibitors (PPI), a class of drugs commonly used to treat acid peptic disorders." (PMID 27203389, 2016). "The absence of acute renal failure in the COVID+ patients in our study suggested the need for additional explanations for increased CgA-release." (PMID 36248786, 2022). "NSE (Cispack NSE, Cis Bio International, Gif-sur-Yvette, France; normal <12.5 microg l(-1)), and chromogranin A (CgA-Riact, Cis Bio International, normal <100 microg l(-1)) were measured in 128 patients without renal insufficiency." (PMID 9792158, 1998).
carcinoids (20 papers, 2010 to 2025). "Elevated levels of serum CgA have been detected in carcinoids originating from all sites of origin and exhibits diagnostic and prognostic value, despite variable background levels in different populations." (PMID 36903295, 2023). "The sensitivity of the parameter varies depending on the tumor location between 10–100%, with the highest sensitivity observed in gastrinoma, glucagonoma, and carcinoid tumors, whereas the CgA specificity is 68–100%." (PMID 36289922, 2022). "Even several hundred times higher CgA values were recorded in carcinoid tumors and in the cases of liver metastases." (PMID 36289922, 2022). "On immunohistochemical examination, carcinoids are positive for neuroendocrine markers such as Syn, CgA, and CD56." (PMID 33019452, 2020). "NSE, CK, CgA and Syn can be detected by immunohistochemical staining and this method can be used as an adjunct to confirm the presence of a carcinoid tumor." (PMID 25621051, 2015). "In contrast to typical appendiceal carcinoids which stain more homogenously positive for CgA and synaptophysin, GCCs often show a more scattered positivity of the neuroendocrine markers." (PMID 25671432, 2015). "CgA is a maker of carcinoids in general with a high sensitivity (85.7%) and specificity (67.9%), although it can also be detected in SCLCs depending on the clinical stage." (PMID 22269186, 2012). "In a previous paper, we used the CgA promoter to control E1A expression with the intention to develop an Ad5-based oncolytic adenovirus, Ad[CgA-E1A], for carcinoid therapy." (PMID 20111709, 2010). "Serum chromogranin A (CgA) has been the most widely used biomarker in detecting carcinoid tumors." (PMID 36903295, 2023). "The measurement of CgA can be recommended for the continuous surveillance of carcinoid patients." (PMID 22269186, 2012). "In addition, a single tumor showing diffuse cgA positivity was regarded as carcinoid and excluded from the study group." (PMID 20535283, 2010). "Immunohistologic tests showed positive expression of chromogranin A (CgA), Galectin-3, neuron-specific enolase (NSE), and synaptophysin (Syn), which are biomarkers of carcinoid tumors." (PMID 31770214, 2019). "For many years, sieric CgA and urinary 5-HIAA, each of which has a specificity of nearly 100% but a low sensitivity, have been the gold standard for detecting carcinoids and conducting follow-up." (PMID 21801379, 2011). "Metastatic carcinoids and GEP tumors have been shown to have the highest CgA levels." (PMID 37568540, 2023). "The observation that serum CgA was higher and CgB did not change in the CgA+ group is similar to that demonstrated in a carcinoid of the colon." (PMID 33383764, 2020). "The mean serum CgA levels in the subjects with carcinoid tumors, insulinomas, gastrinomas, and non-functioning Pan-NETs were 688 ng/ml, 105 ng/ml, 772 ng/ml and 306 ng/ml, respectively, as compared to the control levels of about 100 ng/ml." (PMID 32020844, 2020). "The maximal serum CgA levels were reported in patients with carcinoid tumors, insulinomas, gastrinomas, and non-functioning Pan-NETs at 5200 ng/ml, 236 ng/ml, 1900 ng/ml, and 14,700 ng/ml, respectively." (PMID 32020844, 2020). "Transduction of freshly isolated hepatocytes with Ad[CgA-Luc-miR122] demonstrated more than 99% reduction of luciferase activity, compared to Ad[CgA-Luc] while no reduction was observed in freshly isolated carcinoid cells." (PMID 20111709, 2010). "Reductions in CgA and other abnormal serum hormones were generally not statistically significant, but patients with carcinoid symptom improvement showed a numerically higher PFS probability than patients without symptom improvement (median PFS 108 weeks vs 48 weeks)." (PMID 31527867, 2019). "However, even carcinoid tumors expressing SYP and CgA may occasionally lack INSM1 expression." (PMID 39937015, 2025).
carcinoids (continued). "Importantly, in carcinoid cells and in BON, the CgA promoter-driven oncolytic viruses, either with or without miR122 target sequences, replicate equally well and follow the pattern of Ad5 wt replication." (PMID 20111709, 2010).
prostate carcinoma (20 papers, 2009 to 2025). A carcinoma that arises from epithelial cells of the prostate gland. "This study was designed to evaluate the prognostic significance of focal chromogranin A (cgA) expression in prostate cancer in a series of cases with autopsy-verified cause of death." (PMID 20535283, 2010). "Similar to several other publications, the present study underlines the importance of focal NED in prostate cancer, as evidenced in initial routine biopsies with immunohistochemical examination of cgA expression." (PMID 20535283, 2010). "There are also studies on the diagnostic value of circulating CgA in the diagnosis of prostate cancer, but there are differences between the results, with some studies showing that circulating CgA levels are higher in prostate cancer patients than in non-prostate cancer patients." (PMID 39975592, 2025). "More studies are needed to clarify the diagnostic role of circulating CgA in prostate cancer." (PMID 39975592, 2025). "We evaluated the prognostic role of circulating CgA in prostate cancer through a systematic and comprehensive search of databases and performed subgroup and sensitivity analysis to demonstrate the reliability and stability of the results." (PMID 39975592, 2025). "Circulating CgA is a predictive marker of poor survival outcomes in prostate cancer However, the sample size of the current study is small and larger studies are needed to further validate this in the future." (PMID 39975592, 2025). "Overall, elevated circulating CgA was associated with poorer OS and PFS in prostate cancer, according to our pooled results." (PMID 39975592, 2025). "Elevated tissue and/or blood levels of CgA in diseases such as ulcerative colitis (UC) or prostate cancer can be partially explained because of an increased number of cells that secrete CgA, induced by cytokines such as IFN-γ, IL-1β, IL-6, or TNF." (PMID 40370467, 2025). "Our study aimed to investigate the prognostic role of circulating CgA in prostate cancer, with a meta-analysis of 10 included studies." (PMID 39975592, 2025). "If the detection methods of CgA are standardized and the tumor heterogeneity is classified, CgA is likely to play a very important role as a key factor in the prognosis of prostate cancer." (PMID 39975592, 2025). "First, CgA can promote the proliferation of prostate cancer cells by activating intracellular signaling pathways." (PMID 39975592, 2025). "Studies have found that CgA can bind to specific receptors on the surface of prostate cancer cells and activate the downstream PI3K-Akt signaling pathway." (PMID 39975592, 2025). "There are discrepancies between the results of different studies regarding the prognostic role of circulating Chromogranin A (CgA) in prostate cancer." (PMID 39975592, 2025). "This review aims to evaluate evidence for the usefulness of CgA assessments during the monitoring of prostate cancer." (PMID 36527470, 2023). "Neuroendocrine differentiation (NED) characterized by the expression of neuroendocrine markers, such as chromogranin A (CgA), is frequently observed in advanced prostate cancer (PCa), the prognostic significance of which is still controversial." (PMID 37240468, 2023). "In fact, elevated CgA levels in patients with prostate cancer has reportedly been correlated with the disease stage." (PMID 34943638, 2021). "CGA gene was identified as a new estrogen receptor a (ERa) responsive gene in human breast cancer cells and a member of a novel dysregulated pathway in prostate cancer." (PMID 33072067, 2020).
prostate carcinoma (continued). "Without castration treatment, N-Myc overexpressing LNCaP xenografts displayed more neuroendocrine prostate cancer phenotypes (indicated by CgA and NSE staining) than control LNCaP xenografts which showed more PCA phenotypes (indicated by AR and PSA staining)." (PMID 30657058, 2019). "The increased transgene expression from Ad[CgA-LUC] in the prostate cancer cell lines LNCaP and PC346-C and the decreased expression of Ad[i/PPT-LUC] upon HDACi treatment led us to further investigate the effect of FK228 or VPA on these cell lines." (PMID 21379379, 2011). "The aim of our study was to analyzed the incidence of pre-operative circulating CgA in a population of non metastatic prostate cancer patients." (PMID 21162758, 2010). "Further supporting this uncovered role for SphK1 during the transition to the hormone-refractory state, immunohistochemical studies of prostate cancer human samples showed for the first time that CgA positive-NE cells co-expressed SphK1." (PMID 19956567, 2009). "If the CgA level was slightly elevated, and the PSA level was between 10-20 ng/mL, Gleason score was 7, and clinical stage was T2b-T2c, it was classified as intermediate-risk prostate cancer." (PMID 39975592, 2025). "This suggested that circulating CgA can provide prognostic value in prostate cancer." (PMID 39975592, 2025). "It is suggested that circulating CgA is associated with positive immunohistochemical CgA expression and may serve as a supplement to PSA and provide important information on prostate cancer disease prognosis." (PMID 39975592, 2025). "If the level of CgA was significantly increased, accompanied by PSA > 20 ng/mL, Gleason score ≥8, clinical stage of T3-T4 or regional lymph node metastasis, it was considered as high-risk prostate cancer and highly suspected as neuroendocrine prostate cancer." (PMID 39975592, 2025). "Controversy exists regarding the value of circulating CgA in prostate cancer prognosis." (PMID 39975592, 2025). "Second, CgA can enhance the invasion and metastasis of prostate cancer cells, which is reflected in the regulation of the expression of migration and invasion related molecules in prostate cancer cells." (PMID 39975592, 2025). "In addition, the degree of neuroendocrine differentiation of prostate cancer varies, and only part of the tumor cells with neuroendocrine differentiation characteristics will secrete a large amount of CgA." (PMID 39975592, 2025). "The biological role of CgA in prostate cancer progression includes the following aspects." (PMID 39975592, 2025). "This review was based on three recent meta-analysis concerning CgA and prostate cancer." (PMID 36527470, 2023). "This evidence highlighted the importance of serum CgA monitoring in prostate cancer patients." (PMID 21162758, 2010). "We analyzed serum CgA levels in patients who were diagnosed with a prostate cancer before surgery." (PMID 21162758, 2010). "In addition to morphological characteristics, transdifferentiated NE-like prostate cancer cells are defined by the expression of a number of neurosecretory products including chromogranin A (CgA) and neuron-specific enolase (NSE)." (PMID 19956567, 2009). "Therefore, this study aimed to meta-analyze published results to investigate whether circulating CgA can provide useful prognostic information in prostate cancer." (PMID 39975592, 2025). "Therefore, more and larger studies may be needed in the future to confirm the prognostic role of circulating CgA in prostate cancer." (PMID 39975592, 2025). "The disadvantage of CgA is that it can be false positive in chronic gastritis, inflammatory bowel disease, pancreatitis, renal or liver failure, other malignancies (thyroid and prostate cancer) or different therapies (proton pump inhibitors, somatostatin analogues or steroids)." (PMID 39941198, 2025).